RTN4 (reticulon 4)
Diseases named in the same sentence as RTN4 in open-access papers (continued):
Sharing a sentence is not in itself a finding about the gene and the disease.
cancer (38 papers, 2010 to 2026). A tumor composed of atypical neoplastic, often pleomorphic cells that invade other tissues. "The reticulon-4 (RTN4) gene, encoding Nogo proteins, plays a critical role in apoptosis and cancer development, with genetic variations affecting its function." (PMID 37511924, 2023). "Nogo-B (neurite outgrowth inhibitor B), encoded by reticulon-4, has been shown to be associated with the progression and advanced stage of several cancer types." (PMID 35075114, 2022). "With α-MG as a specific RTN4 chemical degrader, we found that α-MG obviously decreased RTN4 expression for promoting ER tubules-to-sheets transition, subsequently causing pyroptosis in cancer cells." (PMID 39252612, 2025). "Apart from RTN4’s suggested oncogenic roles, polymorphisms in RTN4 may influence its expression and function, leading to pathologic conditions like cancer." (PMID 37511924, 2023). "On the other hand, genetic variations in RTN4 may change its expression pattern and result in pathologic events associated with cancer." (PMID 37511924, 2023). "The expression level of RTN4 was associated with patients' survival for several cancers." (PMID 34589136, 2021). "In vivo, we observed that chemical or genetic RTN4 knockdown significantly inhibited cancer cells growth, which further exhibited an antitumor immune response with anti-programmed death-1 (anti-PD-1)." (PMID 39252612, 2025). "High expression of RTN4 was correlated with proliferation, tumorigenesis and patient survival in multiple types of human cancers." (PMID 39969103, 2025). "Previous reports have shown that targeting RTN4 with chemical small molecules can impair ER and nuclear envelope morphology in cancer cells." (PMID 39252612, 2025). "We observed that chemically induced proteasome degradation of RTN4 by α-MG through recruiting E3 ligase UBR5 significantly enhances the pyroptosis phenotype in cancer cells." (PMID 39252612, 2025). "Flow cytometry analysis demonstrated that downregulation of RTN4 in these cancer cells led to cell cycle arrest primarily in the G0/G1 phase, particularly in the sub‐G1 phase, indicative of apoptotic cells." (PMID 39969103, 2025). "Here we have evaluated the expression of IGF1, CCL5, IL-8, VCAN and RTN4 in peritumoral AT of women with BC, to investigate their potential role as markers of cancer progression." (PMID 39501160, 2024). "On top of that, RTN4/Nogo is also suggested to be pro-oncogenic by modulating signaling pathways critically involved in cancer development, such as PI3K/AKT and MAPK/ERK." (PMID 37511924, 2023). "Nogo-B (Reticulon 4B) is reportedly a regulator of angiogenesis during the development and progression of cancer." (PMID 35383153, 2022). "For example, knockdown of RTN4 (Nogo) destabilizes tubulins and prompts paclitaxel-induced cytotoxicity in cancers." (PMID 34638704, 2021). "RTN4 has been demonstrated to induce apoptosis in cancer cells but play an opposite role in normal cells." (PMID 33557409, 2021). "So far, validated targets of mir-21 included programmed cell death 4 gene (PDCD4), tropomyosin 1 (TPM1), phosphatase and tensin homolog (PTEN), chromosome condensation protein G (NCAPG), reticulon 4 isoform A (RTN4) and other cancer-related genes." (PMID 25098165, 2014). "mir-21 was found to be over expressed in multiple cancers down regulated tumor suppressor genes (TPM1, PTEN, PDCD4 BASP1 and RTN4) in invasion and metastasis of cancer." (PMID 21114830, 2010). "Furthermore, the knockdown of RTN4 retarded the proliferation of cancer cells and mouse tumour xenografts in vitro." (PMID 39969103, 2025). "Similarly, it is suggested that rs34917480 can dysregulate the RTN4/Nogo isoform’s expression, leading to several diseases, particularly cancers." (PMID 37511924, 2023). "SFPQ, RTN4, RICTOR, LARP6, and HELLS are all associated with cancer." (PMID 37569873, 2023). "For instance, it is tantalizing to speculate in how far TMEM147 expression may be therapeutic in cancer by limiting RTN4 action." (PMID 34638576, 2021).
cancer (continued). "Similarly, RTN4 (Nogo) knockdown results in the destabilization of tubulins in cancer cells, indicating that Nogo promotes tubulin stability in cancer cells." (PMID 34638704, 2021). "Reticulon-4 (RTN4) has an essential role in cancer development and progression." (PMID 34589136, 2021). "Moreover, we have analysed peritumoral AT VCAN and RTN4 following a large in silico study mainly based on transcriptomic and proteomic data that have reported their presence in mammary AT secretome and their contribution to cancer phenotypes." (PMID 39501160, 2024). "Also, RTN4 promotes cancer progression by facilitating tumor proliferation and drug resistance." (PMID 34983537, 2022). "RTN4 was involved in many cell activities, such as cell proliferation, differentiation, and apoptosis, and malfunctioning of these mechanisms could lead to cancer development." (PMID 35030979, 2022). "For ERRFI1, RTN4, PHF7, SPRY4, CCND2, and RPL19, H3K36me3 and H3K79me2 enriched higher signals in normal cell lines than that in cancer cells, and the signals of H3K79me2 changed more significantly than H3K36me3 during tumorigenesis." (PMID 37426199, 2023). "IIPA found that SFPQ interacts with many important proteins, such as YY1, RTN4, RICTOR, HDACs, BMI1, and HNRNPC, which are important in the development of cancer." (PMID 35707369, 2022). "Moreover, in a sphingolipid-dependent manner, downregulation of RTN4 led to disruption of the localization of AKT in the plasma membrane, due to which AKT phosphorylation, which is involved in many cancers, was significantly reduced." (PMID 36354672, 2022). "More specifically, therapeutic modulation of FN1, TPT1, RTN4, and FSTL1, for which knockdown has been shown to result in reduced cell proliferation and migration in cancer cells, may represent new potential therapeutic avenues for pterygia as well." (PMID 35174178, 2021).
tumor (28 papers, 2013 to 2025). "The findings suggested that RTN4 might be implicated in the PI3K_AKT_mTOR pathway, cellular responses to hypoxia and inflammatory responses in the genesis and progression of tumours." (PMID 39969103, 2025). "Additionally, a Sankey plot demonstrated robust associations between sex, tumour grade, survival status and RTN4 expression." (PMID 39969103, 2025). "Further, we examined the association between RTN4 rs34917480 and clinicopathological features of BC, including the age and tumor size at the time of diagnosis, histological subtype, grade and stage, and the status of estrogen receptor (ER), progesterone receptor (PR), and HER2 receptors of patients." (PMID 37511924, 2023). "Notably, we assume that this tumor suppressor role (suggested to be intensified by this polymorphism) might reduce or overcome the oncogenic role of RTN4/Nogo isoforms induced by PI3K/AKT and MAPK/ERK activation." (PMID 37511924, 2023). "RTN4 expression in the tumour group was higher than in the normal group (p < 0.001), and a high‐expression level was linked to a poor prognosis (p = 0.028)." (PMID 39969103, 2025). "To evaluate the antitumor potential of RTN4-targeting strategy, we established a 3D tumor spheroids model stained by Calcein-AM and EthD-1." (PMID 39252612, 2025). "In translational research, RTN4 high expression was closely correlated with the tumor metastasis and death of patients." (PMID 39252612, 2025). "Subsequently, we verified this phenomenon in 40 pairs of HCC tissues collected, and the results revealed that RTN4 exhibited low expression in tumor tissues (P < 0.001)." (PMID 35030979, 2022). "Conversely, the alteration of RTN4 mRNA level was heterogeneous, which was marginally increased in tumour tissues from TCGA-STAD and GSE13861 datasets but downregulated in GES13911 dataset." (PMID 35428758, 2022). "It has been known that PTBP1 induces skipping of RTN4 exon 3, generating the transcript (RTN4-B) for the Nogo-B protein which promotes tumor angiogenesis, epithelial-mesenchymal transition, cell migration, and proliferation." (PMID 34548489, 2021). "Thirdly, what was the role of RTN4 within the tumour microenvironment?" (PMID 39969103, 2025). "GSEA further corroborated that RTN4 is involved in LGG progression via tumour‐related signalling pathways and inflammatory responses, indicating that targeted modulation of RTN4 could serve as a potential therapeutic strategy for LGG treatment." (PMID 39969103, 2025). "Human protein array analyses identified cellular targets of XON9, such as solute carrier family 3 member 2 (SLC3A2), annexin A5 (ANXA5), fatty acid synthase (FASN) or reticulon 4 (RTN4) involved notably in tumor progression, angiogenesis, cell growth or apoptosis." (PMID 41009747, 2025). "The specific benefit of RTN4-mediated pyroptosis in enhancing the efficacy of antitumor immune therapy lies in its capacity to increase the expression of PD-L1 in tumor cells and subsequently induce immune-mediated tumor cell death." (PMID 39252612, 2025). "qPCR showed discrepancies for RTN4, possibly due to differences in normalization methods, biological variability (tumor heterogeneity, necrosis), technical variations (RNA extraction, reverse transcription efficiency, degradation), and post-transcriptional regulation." (PMID 40284018, 2025). "For instance, the neurite outgrowth inhibitor (Nogo) of RTN4 could play a newfound role in carcinogenesis through AKT signaling pathway, and knockdown of RTN4 could postpone tumor proliferation in mice." (PMID 31118022, 2019). "Specifically, the question of whether overexpression of the RTN4 gene actually drives LGG progression by modulating the PI3K/Akt signalling pathway and inflammatory response, ultimately altering the tumour microenvironment, remains unanswered." (PMID 39969103, 2025).
tumor (continued). "Studies have revealed that RTN4 is down-regulated in HCC tissues and cell lines, and high expression of RTN4 might inhibit the growth and proliferation of HCC and promote tumor apoptosis." (PMID 35030979, 2022).
neurodegenerative disease (9 papers, 2013 to 2023). A disorder of the central nervous system characterized by gradual and progressive loss of neural tissue and neurologic function. "Moreover, the comparative analysis of RTN4 concentration between different neurodegenerative diseases revealed the highest concentration of RTN4A in AD patients and a statistically significant difference between AD vs. PD, and AD vs. MS groups." (PMID 34830564, 2021). "However, a higher concentration of RTN-4 was observed in patients with neurodegenerative diseases (AD, PD) than in subjects with MS or the control group." (PMID 34830564, 2021). "Therefore, the purpose of the present investigation was to measure the RTN-4 levels in cerebrospinal fluid patients with different neurodegenerative diseases and controls and verify a potential clinical usefulness of this protein." (PMID 34830564, 2021). "Therefore, we aimed to assess the cerebrospinal fluid (CSF) concentrations of Reticulon 4 (RTN4) in patients with neurodegenerative diseases and evaluate the potential clinical usefulness of this protein." (PMID 34830564, 2021). "Moreover, the comparative analysis of CSF RTN4 levels revealed significantly higher concentrations in patients with neurodegenerative diseases, particularly with AD." (PMID 34830564, 2021).
neurological diseases (8 papers, 2015 to 2023). "We observed increased levels of the RTN4 protein in CSF patients with neurological diseases." (PMID 34830564, 2021).
infection (6 papers, 2016 to 2025). The state of being infected such as from the introduction of a foreign agent such as serum, vaccine, antigenic substance or organism. "Our transcriptional analysis suggests that upon infection, there is an upregulation at the transcript level of ER shaping proteins such as Reticulon-4a (RTN4A, essential for maintaining ER tubules)." (PMID 40272166, 2025).
RTN4 also shares sentences with these, for which no sentence is quoted: amyotrophic lateral sclerosis (12 papers); ischemic stroke (11); Cerebral ischemia (8); ischemia (7); Parkinson disease (7); cervical cancer (6); experimental autoimmune encephalomyelitis (6); myocardial infarction (6); atherosclerosis (5); brain injury (5); Hypertension (5); cardiovascular diseases (4); cognitive decline (4); liver disease (4); alcoholic liver diseases (3); Anxiety (3); cardiac diseases (3); Cirrhosis (3); coronary heart disease (3); fibrosis (3); meningeal tumor (3); myocardial ischemia (3); myopathy (3); oligodendroglioma (3); retinal diseases (3); temporal lobe epilepsy (3); acute lung injuries (2); chronic asthma (2); demyelination (2); diabetic retinopathy (2).
A further 95 diseases each share a sentence with RTN4 in 2 papers or fewer.